CELP (carboxyl ester lipase pseudogene)
Synonyms: CELL; cell1; cell2; cell3
Gene: Transcribed unprocessed pseudogene on chromosome 9 (133,082,561 to 133,087,253, forward strand). Ensembl gene ENSG00000170827.
Diseases named in the same sentence as CELP in open-access papers:
CELP is named in the same sentence as 1 disease in open-access papers, as found by Europe PMC text mining. Sharing a sentence is not in itself a finding about the gene and the disease. The quoted sentences say what the papers report.
chronic pancreatitis (4 papers, 2017 to 2022). A chronic inflammatory process causing damage and fibrosis of the pancreatic parenchyma. "CEL-HYB1, a hybrid allele of CEL and its adjacent pseudogene CELP, is a genetic variant suggested to increase the risk of chronic pancreatitis (CP)." (PMID 36379850, 2022). "Another report shows that a recombined allele of CEL and its pseudogene CELP confers susceptibility to chronic pancreatitis." (PMID 30305605, 2018). "CEL-HYB is a hybrid allele that arose from a crossover between the 3’ end of the Carboxyl ester lipase (CEL) gene and the nearby CEL pseudogene (CELP) and was recently identified as a risk factor for chronic pancreatitis." (PMID 28881607, 2017). "Additionally, non-allelic homozygous recombination of CEL and its neighboring pseudogene CELP results in a hybrid protein CEL-HYB1 characterized by impaired activity, secretion defect, misfolding, and increased susceptibility for chronic pancreatitis." (PMID 35704637, 2022).